PLPP3 (phospholipid phosphatase 3)
Description:
Magnesium-independent phospholipid phosphatase of the plasma membrane that catalyzes the dephosphorylation of a variety of glycerolipid and sphingolipid phosphate esters including phosphatidate/PA, lysophosphatidate/LPA, diacylglycerol pyrophosphate/DGPP, sphingosine 1-phosphate/S1P and ceramide 1-phosphate/C1P. Also acts on N-oleoyl ethanolamine phosphate/N-(9Z-octadecenoyl)- ethanolamine phosphate, a potential physiological compound. Has both an extracellular and an intracellular phosphatase activity, allowing the hydrolysis and the cellular uptake of these bioactive lipid mediators from the milieu, regulating signal transduction in different cellular processes. Through the dephosphorylation of extracellular sphingosine-1-phosphate and the regulation of its extra- and intracellular availability, plays a role in vascular homeostasis, regulating endothelial cell migration, adhesion, survival, proliferation and the production of pro-inflammatory cytokines. By maintaining the appropriate levels of this lipid in the cerebellum, also ensure its proper development and function (By similarity). Through its intracellular lipid phosphatase activity may act in early compartments of the secretory pathway, regulating the formation of Golgi to endoplasmic reticulum retrograde transport carriers. Independently of this phosphatase activity may also function in the Wnt signaling pathway and the stabilization of beta-catenin/CTNNB1, thereby regulating cell proliferation, migration and differentiation in angiogenesis or yet in tumor growth. Also plays a role in integrin-mediated cell-cell adhesion in angiogenesis.
Synonyms: PAP-2b; PAP2b; VCIP; LPP3; PPAP2B; Dri42
Tractability: Antibody: UniProt places it where antibodies can reach, with high confidence; its Gene Ontology location is reachable by antibodies, with high confidence; UniProt predicts a signal peptide or a membrane-spanning region. PROTAC: ubiquitination databases record sites on it; its protein half-life has been measured.
Gene: Protein-coding gene on chromosome 1 (56,494,761 to 56,645,301, reverse strand). Ensembl gene ENSG00000162407.
Subcellular location: Cell membrane; Basolateral cell membrane; Endoplasmic reticulum membrane; Endoplasmic reticulum-Golgi intermediate compartment membrane; Golgi apparatus membrane; Golgi apparatus, trans-Golgi network membrane; Membrane raft
Subcellular location (Human Protein Atlas): Golgi apparatus; Mid piece; Principal piece
Pathways (Reactome):
Metabolism: Sphingolipid catabolism
Gene Ontology:
Molecular function: ceramide-1-phosphate phosphatase activity; delta-catenin binding; integrin binding; phosphatidate phosphatase activity; protein binding; sphingosine-1-phosphate phosphatase activity; lipid phosphatase activity
Biological process: cell-cell adhesion mediated by integrin; ceramide metabolic process; integrin-mediated signaling pathway; phospholipid dephosphorylation; phospholipid metabolic process; positive regulation of endothelial cell migration; positive regulation of endothelial cell-matrix adhesion; positive regulation of homotypic cell-cell adhesion; positive regulation of intracellular signal transduction; positive regulation of transcription by RNA polymerase II; protein stabilization; retrograde vesicle-mediated transport, Golgi to endoplasmic reticulum; sphingosine metabolic process; cell-cell adhesion; signal transduction; sphingolipid catabolic process
Cellular component: adherens junction; basolateral plasma membrane; endoplasmic reticulum exit site; endoplasmic reticulum membrane; endoplasmic reticulum-Golgi intermediate compartment membrane; Golgi apparatus; Golgi membrane; membrane; membrane raft; plasma membrane; trans-Golgi network
Genetic constraint (gnomAD): Loss-of-function variants: 6 observed, 29.39 expected, observed/expected ratio (o/e) 0.2, 90% interval 0.11 to 0.4. The upper end of that interval is the gene's LOEUF score, 0.4, which puts it in group 1 of 6, group 1 being the genes least tolerant of losing a copy. Missense variants: 308 observed, 420.04 expected, observed/expected ratio (o/e) 0.73, 90% interval 0.67 to 0.81. Synonymous variants: 152 observed, 163.95 expected, observed/expected ratio (o/e) 0.93, 90% interval 0.81 to 1.06.
Homologues: Orthologues: chimpanzee PLPP3 (99% identical), macaque PLPP3 (99% identical), dog PLPP3 (97% identical), mouse Plpp3 (95% identical), rat Plpp3 (95% identical), guinea pig PLPP3 (91% identical), rabbit PLPP3 (85% identical), pig PLPP3 (83% identical), tropical clawed frog plpp3 (78% identical), zebrafish plpp3 (72% identical), Drosophila melanogaster wun (39% identical), Caenorhabditis elegans plpp-1.1 (34% identical), and 7 more. Paralogues in human: PLPP1 (48% identical), PLPP2 (43% identical), PLPPR4 (26% identical), PLPPR1 (25% identical), PLPPR3 (24% identical), PLPPR5 (24% identical), PLPPR2 (22% identical), PLPP5 (21% identical), PLPP4 (21% identical).